RNU6-397P (RNA, U6 small nuclear 397, pseudogene)
Gene: Small nuclear RNA gene on chromosome 8 (14,487,776 to 14,487,879, reverse strand). Ensembl gene ENSG00000252035.
Homologues: Orthologues: chimpanzee U6 (87% identical). Paralogues in human: RNU6-1222P (73% identical), RNU6-326P (73% identical), RNU6-820P (73% identical), RNU6-884P (73% identical), RNU6-1152P (72% identical), RNU6-19P (72% identical), RNU6-310P (72% identical), RNU6-417P (72% identical), RNU6-454P (72% identical), RNU6-49P (72% identical), RNU6-549P (72% identical), RNU6-656P (72% identical), and 1286 more.